BUD23 (BUD23 rRNA methyltransferase and ribosome maturation factor)
Description:
S-adenosyl-L-methionine-dependent methyltransferase that specifically methylates the N(7) position of a guanine in 18S rRNA. Requires the methyltransferase adapter protein TRM112 for full rRNA methyltransferase activity. Involved in the pre-rRNA processing steps leading to small-subunit rRNA production independently of its RNA-modifying catalytic activity. Important for biogenesis end export of the 40S ribosomal subunit independent on its methyltransferase activity. Locus-specific steroid receptor coactivator. Potentiates transactivation by glucocorticoid (NR3C1), mineralocorticoid (NR3C2), androgen (AR) and progesterone (PGR) receptors. Required for the maintenance of open chromatin at the TSC22D3/GILZ locus to facilitate NR3C1 loading on the response elements. Required for maintenance of dimethylation on histone H3 'Lys-79' (H3K79me2), although direct histone methyltransferase activity is not observed in vitro.
Synonyms: MERM1; WBSCR22; PP3381; MGC19709; MGC2022; MGC5140; WBMT; HASJ4442; HUSSY-3
Tractability: Small molecule: a structure with a bound ligand is known. PROTAC: UniProt records ubiquitination sites on it; ubiquitination databases record sites on it.
Gene: Protein-coding gene on chromosome 7 (73,683,568 to 73,698,228, forward strand). Ensembl gene ENSG00000071462.
Subcellular location: Nucleus; Nucleus, nucleoplasm; Cytoplasm, perinuclear region; Cytoplasm
Subcellular location (Human Protein Atlas): Nucleoli; Nucleoplasm
Pathways (Reactome):
Metabolism of RNA: Major pathway of rRNA processing in the nucleolus and cytosol; rRNA modification in the nucleus and cytosol
Gene Ontology:
Molecular function: protein binding; protein heterodimerization activity; RNA binding; rRNA (guanine) methyltransferase activity; methyltransferase activity; S-adenosylmethionine-dependent methyltransferase activity
Biological process: positive regulation of rRNA processing; rRNA (guanine-N7)-methylation; rRNA processing
Cellular component: cytoplasm; nucleolus; nucleoplasm; nucleus; perinuclear region of cytoplasm; tRNA methyltransferase complex
Genetic constraint (gnomAD): Loss-of-function variants: 34 observed, 49.4 expected, observed/expected ratio (o/e) 0.69, 90% interval 0.52 to 0.92. The upper end of that interval is the gene's LOEUF score, 0.92, which puts it in group 3 of 6, group 1 being the genes least tolerant of losing a copy. Missense variants: 343 observed, 381.79 expected, observed/expected ratio (o/e) 0.9, 90% interval 0.82 to 0.98. Synonymous variants: 124 observed, 140.86 expected, observed/expected ratio (o/e) 0.88, 90% interval 0.76 to 1.02.
Homologues: Orthologues: chimpanzee BUD23 (99% identical), macaque BUD23 (99% identical), pig BUD23 (85% identical), rabbit BUD23 (83% identical), dog BUD23 (82% identical), guinea pig BUD23 (79% identical), mouse Bud23 (79% identical), rat Bud23 (79% identical), zebrafish bud23 (64% identical), tropical clawed frog bud23 (58% identical), Drosophila melanogaster CG10903 (57% identical), Caenorhabditis elegans C27F2.4 (48% identical).
Diseases named in the same sentence as BUD23 in open-access papers:
BUD23 is named in the same sentence as 20 diseases in open-access papers, as found by Europe PMC text mining. Sharing a sentence is not in itself a finding about the gene and the disease. The quoted sentences say what the papers report.
Williams-Beuren syndrome (7 papers, 2014 to 2025). "BUD23, a highly conserved ribosomal RNA methyltransferase which lies within a multigene interval, deleted as a cause of Williams-Beuren syndrome, plays a specific role in highly ATP-hungry cells, promoting translation of mitochondrial proteins, and impacting on oxidative phosphorylation." (PMID 31939735, 2020). "There is little understanding of the physiological role of BUD23 in a mammalian context although it is one of the genes deleted in Williams-Beuren syndrome (WBS)." (PMID 31939735, 2020). "The BUD23 rRNA methyltransferase and ribosome maturation factor (BUD23/WBSCR22) and 28S rRNA Cytosine-C5-methyltransferase (NSUN5A/WBSCR20) were deleted in Williams-Beuren syndrome." (PMID 37612540, 2023). "As BUD23 impacts the translation of mRNAs with low 5′-UTR GC content and/or certain uORF types this could help explain the variety of symptoms observed in the genetic disease Williams syndrome, in which BUD23 and other genes are deleted." (PMID 40045788, 2025). "People with certain diseases, such as Williams-Beuren syndrome, do not make enough BUD23; but it was unknown what specific effects resulted from a loss of BUD23." (PMID 31939735, 2020).
behavioral disorders (1 paper, 2025). "The significance of the results is in discovering a role for BUD23 in brain laterality and suggesting mechanism-based candidates for neuropsychiatric and behavioral disorders associated with perturbations of laterality." (PMID 40473890, 2025). "The results implicate dosed BUD23, an 18S ribosomal RNA methyltransferase, in human brain laterality, support an evolutionary origin and provide altered lateralization as a novel mechanism for impaired cognition in genetic and behavioral disorders." (PMID 40473890, 2025).
cardiac failure (1 paper, 2020). "Loss of BUD23 in heart and skeletal muscle resulted in early death from cardiac failure." (PMID 31939735, 2020).
cardiomyopathy (1 paper, 2020). A disease of the heart muscle or myocardium proper. "Given the strong mitochondrial deficiencies observed in BUD23-deficient cardiac tissue, we predicted that the cardiomyopathy was the likely cause of sudden death." (PMID 31939735, 2020). "Deletion of Bud23 in murine cardiomyocytes reduced mitochondrial content and function, leading to severe cardiomyopathy and death." (PMID 31939735, 2020). "These discoveries identify BUD23 as essential for mammalian mitochondrial function, with implications for human mitochondrial disease and cardiomyopathy." (PMID 31939735, 2020). "Finally, we examine the role of BUD23 in the mitochondrially-rich and energetically-demanding cardiac tissue and discover a cardiomyopathy phenotype leading to premature death." (PMID 31939735, 2020). "Therefore, BUD23 plays a critical role in coupling protein translation to mitochondrial function, with implications for mitochondrial diseases, and cardiomyopathies." (PMID 31939735, 2020).
dilated cardiomyopathy (1 paper, 2020). Cardiomyopathy which is characterized by dilation and contractile dysfunction of the left and right ventricles. "In mice, cardiomyocyte loss of BUD23 greatly impaired mitochondrial ATP generation leading to dilated cardiomyopathy and premature death, and global loss of BUD23 resulted in embryo-lethality." (PMID 31939735, 2020). "Targeted disruption of Bud23 in cardiac tissue results in dilated cardiomyopathy." (PMID 31939735, 2020).
tumor (9 papers, 2013 to 2025). "BUD23 (previously known as WBSCR22) was initially identified as a putative methyltransferase implicated in tumour metastases." (PMID 31939735, 2020). "Multi-omics analyses revealed consistently elevated expression of AHCY, BUD23, LCMT1, MARS1, METTL6, SCLY and SEPHS1 in various tumor types." (PMID 41441975, 2025).
cancer (5 papers, 2013 to 2025). A tumor composed of atypical neoplastic, often pleomorphic cells that invade other tissues. "Similarly, our work revealed BUD23 expression to be correlated with cancer survival, in agreement with another recent study." (PMID 32375858, 2020).
infection (1 paper, 2023). The state of being infected such as from the introduction of a foreign agent such as serum, vaccine, antigenic substance or organism. "To dissect the impact of BUD23 depletion on the translation of KSHV mRNAs we used ribosome profiling to screen global translation during infection." (PMID 36653366, 2023).
BUD23 also shares sentences with these, for which no sentence is quoted: glioma (4 papers); hepatocellular carcinoma (3); pancreatic cancer (3); breast carcinoma (2); colorectal cancer (1); diabetes mellitus (1); Glucose intolerance (1); invasive breast carcinoma (1); Lung Diseases (1); mitochondrial disease (1); multiple myeloma (1); renal carcinoma (1).